C5 (complement C5)
Diseases named in the same sentence as C5 in open-access papers (continued):
Sharing a sentence is not in itself a finding about the gene and the disease.
tumor (continued). "As thrombin can also cleave C5 in the absence of C3, we evaluated C5 cleavage by immunohistochemical analysis of C5b-9 deposition in tumor tissues, which indirectly reflects the cleavage of C5." (PMID 28106852, 2017). "The reversal of tumor suppression caused by the absence of complement C3, resulting from the immune exhaustion of CD4+ T cells, provides evidence that tumors can drive immune evasion through C3/C5-dependent pathways." (PMID 39958348, 2025). "Beside complement regulators and receptors, components normally produced in the liver, as C1q, C1r, C1s, C3 and C5 are locally synthesized and deposited in different tumor types and in the stroma regardless of complement activation, being predominantly tumorigenic in the majority of cancer types." (PMID 40370471, 2025). "In contrast, C5 expression demonstrated less of a correlation with immune infiltration and correlated positively with the tumor purity, suggesting its confinement to the tumor rather than the immune cells." (PMID 34439277, 2021). "Interestingly, tumor cells but not non-transformed cells produced endogenous C5, and C5a generation took place even in the absence of serum." (PMID 30687327, 2018). "The targets of aptamers actually in clinical trials are extracellular proteins (VEGF165, C5, PDGFβ, coagulation factor IXa, A1 domain of von Willebrand factor, thrombin, TFPI, CXCL12, CCL2, hepcidin peptide hormone), except nucleolin which is highly expressed at the surface of several tumor cells." (PMID 28635657, 2017). "Finally we recently found that tumor cell dedifferentiation is important for metastasis in RT2 mice, and there may be some effect by complement C5 on this process (Kobayashi, Contractor and Harris, unpublished data)." (PMID 27105526, 2016). "Mice lacking a functional gene for complement C5 had smaller primary tumors, which were less invasive and lacked the CD68+ macrophages that have previously been associated with metastasis in this type of tumor." (PMID 27105526, 2016). "After adjustment for tumor purity, DHX37 in LIHC and LUAD showed negative correlations with C3 and other complement regulators but not significantly correlated with C5." (PMID 33490290, 2020). "Therefore, our correlation analysis does not support the role of C3, C5, C3AR1, and C5AR1 in regulating tumor infiltration of TAMs and MDSCs and warrants experimental clarification." (PMID 34439277, 2021).
cancer (39 papers, 2005 to 2026). A tumor composed of atypical neoplastic, often pleomorphic cells that invade other tissues. "Since the iTAAs and complement (C) are associated with cancer therapy Immunofluorescence (IF) was applied to evaluate the expression of the iTAAs and C3, C5, C9." (PMID 37336938, 2023). "A pan cancer multiomics analysis showed that the expression of C3/C5/C3AR1/C5AR1 is associated with the immune evasion signature, indicating the possible immune modulating role of complement proteins in HCC." (PMID 36341431, 2022). "As a consequence, we found cancer stem cell-associated proteins, such as mmp2, mmp9, mmp13, mmp14, paxillin, Ras, src and c-myc, as well as genes expressed in the immune system, such as C5, C9, and HMGB1." (PMID 31832023, 2019). "Although a single case cannot prove an antitumor effect of complement blockade, the experience highlights the practical value of C5 inhibition during intensive chemotherapy and justifies prospective studies in cancer-complicated PNH." (PMID 40827190, 2025). "We need more comprehensive research into the role of complement dysregulation in cancer-related TMAs and the potential benefits of C5 blockade in such settings." (PMID 39518607, 2024). "In a paper reviewing expression of complement in various cancers most cancers over-expressed C3 but neutrally-expressed C5, and the most over expressed gene was CD59, suggesting efficient protection of malignant cells from complement-mediated killing." (PMID 37034706, 2023). "We found that C1ra, C2, and C3 were upregulated in lung fibroblasts incubated with CM of chemotherapy-treated cancer cells, while expression of C5 and CFP was directly upregulated upon incubation with doxorubicin." (PMID 36184683, 2022). "We conducted a gene pathway activity and interaction network analysis to identify the effect of the complement component genes C3, C5, C3AR1, and C5AR1 on 10 major functional and signaling pathways associated with human cancer." (PMID 34439277, 2021). "Among the three cell types promoting T-cell exclusion, MDSCs and the M2 subtype of TAMs are negatively associated with the expression levels of C3, C5, C5AR1, and C3AR1, while only C3 expression shows a positive association with cancer-associated fibroblasts." (PMID 34439277, 2021). "This study is in line with previous observations of an abnormal expression of complement proteins in different type of cancer, especially C1 complex, C3, C4, C5, C3aR, C5aR1, FB, FH, FI, CD46, CD55, CD59." (PMID 33113844, 2020). "In terms of complement’s immunostimulatory vs. immunoregulatory functions and their potential applications in the development of novel therapies for cancer patients, the only complement inhibitors approved are those that act at the C5 level, such as Eculizumab." (PMID 35205837, 2022). "It is worth mentioning that targeting the receptor C5aR rather than the components C3 or C5, allows opsonization to take place in order to protect cancer patients from the risk of acquiring bacterial infections." (PMID 35173724, 2022). "We found that C3, C5, C3AR1, and C5AR1 expression is negatively associated with infiltrations of M2-TAMs and MDSCs but positively associated with CAF infiltrations in various cancer types." (PMID 34439277, 2021). "We found that the complements C3, C5, C3AR1, and C5AR1 have deregulated expression in human malignancies and are associated with activation of immune-related oncogenic processes and poor prognosis of cancer patients." (PMID 34439277, 2021). "Tumor cells may partly contribute to C activation using cell-bound proteases exposed on their surface to cleave C5 and to generate C5a, which in turn enhances cancer cell invasion." (PMID 30319647, 2018). "Moreover, it was reported that C5a was also released without activation of the complement cascade by cleavage of serum C5 by cancer cell membrane-bound proteases, thrombin or various proteases from phagocyte without activation of the complement cascade." (PMID 27756879, 2016).
cancer (continued). "Cancer-associated fibroblasts (CAF) isolated from mouse lungs bearing early-stage breast cancer metastasis 24 h after the last doxorubicin dose, showed significant upregulation of complement genes across the complement pathway, including C1ra, C1s, C2, C3, C4a, C5, C7 and C8a." (PMID 39765018, 2025). "Overall, adipocyte–cancer cell interactions promoted invasiveness and tumorigenesis via lipid transfer, activating the ISR, and upregulating complement proteins C3 and C5." (PMID 39964754, 2025). "LncOVM formed a complex with protein PPIP5K2 and remodeled the structure of Golgi complex, leading to the enhanced complement C5 secretion and MDSC infiltration in TME, which promoted cancer metastasis." (PMID 35813475, 2022). "Collectively, C3, C5, C3AR1, and C5AR1 demonstrated context-dependent expression in and a prognostic impact on various cancer types." (PMID 34439277, 2021). "We used the differential gene expression module of TIMER to evaluate the differential expression of C3, C5, C3AR1, and C5AR1 between human cancer and normal tissues across the TCGA database." (PMID 34439277, 2021). "More biological evidence is required to further understand the role of the complement components C3, C5, C3AR1, and C5AR1 in cancer progression." (PMID 34439277, 2021). "The complement components C3, C5, C3AR1, and C5AR1 serve as attractive targets for strategizing cancer immunotherapy and response follow-up." (PMID 34439277, 2021). "In conclusion, the complement components C3, C5, C3AR1, and C5AR1 serve as attractive targets for strategizing cancer immunotherapy and response follow-up." (PMID 34439277, 2021). "We assessed the correlation of C3, C5, C3AR1, and C5AR1 expression with infiltrations of six types of immune cells across the TCGA cancer types." (PMID 34439277, 2021). "The significantly overexpressed sEV proteins in the BC plasma-derived UCT isolates were ALB, COL1A1, CSN1S1, EEF1A2, and RPL3; and the C1S, C5, C7, and CFHR2 sEV proteins in the UCT isolates were the most downregulated proteins in the BC plasma compared to the non-cancer control." (PMID 37895140, 2023). "Thus, we further examined these genes and found that the mRNA expressions of C3, C5, CFB, and CLU were correlated with cancer stage and prognosis in patients with HCC." (PMID 34813686, 2022). "Collectively, our study demonstrates that the complement component proteins C3, C5, C3AR1, and C5AR1 are candidate biomarkers for cancer diagnosis, prognosis, and therapy outcomes, and thus serve as attractive targets for strategizing cancer immunotherapy and the response follow-up." (PMID 34439277, 2021). "Immune suppression may involve the immune checkpoint pathway, whereby c5, c8, and c9 subtypes tend to show high expression of ligands such as PDL1 and PDL2 (presumably expressed by cancer cells), as well as high expression of the corresponding receptors associated with T cells." (PMID 28775315, 2017).
kidney diseases (15 papers, 2018 to 2026). "Increased tubular complement component 5 (C5) deposition and glomerular C4 were detected in patients with DN, and the intensity of C5 or C4 staining was strongly associated with kidney disease progression in these patients." (PMID 34043214, 2021). "The complement system, and specifically C5, remains a well‐known contributor to various kidney diseases and, in some cases, may perpetuate kidney tissue injury." (PMID 41189475, 2025). "Our 6-month mouse cohort provides us with what we believe to be the clearest evidence to date that long-term C5 inhibition is unlikely to result in an alternative complement-mediated renal disease, despite the presence of deposited C3 within the glomeruli." (PMID 30714990, 2019). "This could explain why not all patients benefit of an anti-C5 therapy in C3-mediated kidney diseases or during strong complement activation." (PMID 29875766, 2018).
bacterial infections (9 papers, 2012 to 2025). "Although inhibition of C5 by neutralizing antibodies has been associated with increased risk of bacterial infection due to the inhibition of the formation of the membrane attack complex, the selective targeting of C5a/C5aR1 signaling may avoid harmful anaphylatoxin-induced effects." (PMID 37104043, 2023). "The downregulated proteins were related to the reduction in markers of inflammation (e.g., Alox5, Lbp, C5, Il36b, and Mmp8) and bacterial infections (e.g., Masp2, Mbl1, Krt34, and Cfd)." (PMID 38030636, 2023). "While C5 inhibition has been discussed from a therapeutic perspective, significant improvements have not been observed to date and must be interpreted in light of concerns about bacterial infection." (PMID 37110438, 2023). "Inhibition of C5 blocks the formation not only of C5a but also of membrane attack complex (MAC) and may be associated with higher risk of bacterial infections requiring, e.g., vaccination against Neisseria meningitidis." (PMID 35880179, 2022). "Importantly, many anti-C5a antibodies also bind C5, thus preventing the formation of the terminal complement complex C5b-9 which is important for controlling bacterial infection." (PMID 23233853, 2012). "Plm can also activate complement but degrade C5, thereby preventing C5b deposition and MAC formation, which is a powerful lytic agent in bacterial infections." (PMID 30166455, 2018).
infectious disease (5 papers, 2008 to 2022). A disorder directly resulting from the presence and activity of a microbial, viral, or parasitic agent in humans. "For example, the different role of C5aR1 and C5aR2 inhibition in these diseases is poorly understood, and inhibition of C5 activation for prolonged time periods results in increased susceptibility to infectious diseases and other undesired effects." (PMID 33917266, 2021). "Given its central role in innate immunity, targeting of complement C5 might also lead to infectious disease, so it will be important to determine if a risk of infectious disease might be outweighed by the potential benefit of preventing metastasis in certain patients." (PMID 27105526, 2016). "In this sense, it has been demonstrated that activated T cells display a complement C5 protein-dependent NLRP3 inflammasome assembly, which induces T helper 1 (Th1) responses, which are typically associated with autoimmune and infectious diseases." (PMID 36248890, 2022). "This suggests a role of complement factors C1q and C5 in the neuropathology of CM and emphasizes the importance of the host immune response in this neuro-infectious disease." (PMID 18847493, 2008).
kidney (4 papers, 2016 to 2026). "In recent years, complement 5 (C5) and its anaphylatoxin receptor C5aR1 have been implicated in driving kidney IRI and loss of function." (PMID 42210713, 2026).
immune disorders (3 papers, 2019 to 2025). "Interestingly, the majority of pathways affected by complement C5 were linked to innate immune disorders and inflammation." (PMID 33280239, 2021).
myopathy (3 papers, 2022 to 2025). A disease of the muscle in which the muscle fibers do not function properly. "To confirm the essential role of human C5 activation in anti-HMGCR+-driven myopathy, we repeated the same experiment as above using C57BL/6 recipient mice." (PMID 36009583, 2022). "Together, these data confirm that C5 is required to induce myopathy and that the inhibition of human C5 activation is effective in preventing IMNM in this humanized mouse model." (PMID 36009583, 2022). "Therefore, in order to investigate the role of C5 activation in experimental myopathy, we transferred IgG-depleted normal human serum as a source of complement to C5def mice followed by the administration of purified anti-HMGCR+ or control IgG every two days." (PMID 36009583, 2022).
vasculopathy (3 papers, 2020 to 2022). "Eculizumab, a C5 inhibitor, is a complement-targeting approved drug for a variety of vascular disorders and has recently been approved in kidney diseases." (PMID 36198672, 2022).
cardiovascular disease (2 papers, 2022 to 2024). "A BET inhibitor was recently reported to downregulate basal and cytokine-simulated expression of complement components in cultured hepatocytes and humanized mice, and to reduce activated complement C3 and C5 levels in the circulation of cardiovascular disease patients." (PMID 39294122, 2024).
cardiac disease (1 paper, 2019). "It is formed during the cleavage of C5 in the complement system cascade and is involved in many cardiac disease states." (PMID 31247004, 2019).
diseases of the central nervous system (1 paper, 2020). "Generating single‐chain variable or other small recombinant fragments from the CDRs of BB5.1 may allow proof‐of‐concept studies for C5 blockade in diseases of the central nervous system where the blood–brain barrier is grossly intact, blocking ingress of intact mAbs." (PMID 32557571, 2020).
neurodevelopmental disorder (1 paper, 2021). A behavioral and cognitive disorder with onset during the developmental period that involves impaired or aberrant development of intellectual, motor, or social functions. "The associated SNPs map at the highly conserved ASTN2/BRINP1 locus at chr9q33.1–33.2, which contains five genes (ASTN2, BRINP1, TRIM32, TLR4 and C5) that have been previously associated with neurodevelopmental disorders (reviewed in29)." (PMID 34267256, 2021).
peripheral neuropathy (1 paper, 2021). A disorder affecting the peripheral nervous system. "Here, we provide an overview of complement pathways and major components associated with dysregulated complement activation in peripheral neuropathy, and of drugs under development targeting the C5 system." (PMID 33917266, 2021). "C5/C5aR1 axis modulators could represent a new strategy to treat complement-related peripheral neuropathies." (PMID 33917266, 2021).
psychiatric disorder (1 paper, 2015). A disorder characterized by behavioral and/or psychological abnormalities, often accompanied by physical symptoms. "However, to what extent the TRPC4/C5 channels are involved in psychiatric disorders remains unexplored." (PMID 26317356, 2015).
C5 also shares sentences with these, for which no sentence is quoted: allergic disease (3 papers); glomerulopathy (3); neurodegenerative disease (3); neurological diseases (3); pancreatic cancer (3); respiratory failure (3); acute myocardial infarction (2); allergies (2); antiphospholipid syndrome (2); blood disorder (2); Cerebral ischemia (2); cystic fibrosis (2); end-stage renal disease (2); experimental autoimmune encephalomyelitis (2); juvenile idiopathic arthritis (2); liver cancer (2); primary immunodeficiency (2); Protein-losing enteropathy (2); retinopathies (2); thrombophilia (2); abortion (1); adenocarcinoma (1); adenovirus infection (1); Amyloid (1); Arterial thrombosis (1); Atrophy (1); autoimmune peripheral neuropathy (1); autoimmune uveitis (1); Becker muscular dystrophy (1); bipolar disorder (1).
A further 77 diseases each share a sentence with C5 in 1 paper.